CDH17 (cadherin 17)
Diseases named in the same sentence as CDH17 in open-access papers (continued):
Sharing a sentence is not in itself a finding about the gene and the disease.
cancer (continued). "Survival analysis revealed two methylation sites localised at the CDH17 and LRP2 genes, respectively, to be able to predict risk of cancer recurrence." (PMID 36612154, 2022). "The aberrant expression has resulted in the attempts to use CDH17 as a target for cancer imaging and therapy." (PMID 36435809, 2022). "Pathophysiologically, the expression of CDH17 has been extensively explored in various cancers from digestive system." (PMID 36435809, 2022). "CDH17 is expressed in epithelial cells of the intestine, kidney, and developing brain, as well as in memory B cells and is misregulated in numerous cancers." (PMID 36612154, 2022). "Cadherin-17 (CDH-17), a cell surface biomarker specific for gastrointestinal cancers, is a cell−cell adherent junctional molecule and plays an important role in cancer cell adhesion, progression, and metastasis." (PMID 34064074, 2021). "The positive CDH17 ratios were 63.6% (7/11) for grade 2 and 56.5% (13/23) for grade 3 in the primary cancer specimens, and 86.7% (6/7) for grade 2 and 51.9% (14/27) for grade 3 in the LN metastasis specimens." (PMID 31605356, 2020). "The percentage of CDH17-positive primary cancer and CDH17-negative LN metastasis [primary (+)/LN (−)] specimens was 20% (4/20)." (PMID 31605356, 2020). "In the CDH17-stained sections, the percentage of CDH17-positive primary cancer and positive LN metastasis [primary (+)/LN (+)] specimens was 80.0% (16/20)." (PMID 31605356, 2020). "Multiple cancer survival-related genes were found in these genes, including CDH17, PTPRJ, SLC16A14, TMTC2, and NOTCH4." (PMID 32426342, 2020). "This RGD motif in CDH17 and VE-cadherin enables the activation of α2β1 integrin in different cancers and the activation of αIIbβ3 integrin in CDH6-expressing tumors (manuscript in preparation)." (PMID 31324051, 2019). "Then, we described the interaction of CDH17 and VE-cadherin with α2β1 integrin in different cellular contexts and cancer models." (PMID 31324051, 2019). "Mutations in cis-acting splicing elements were shown in both oncogenes (KIT, CDH17, and BRCA1/2) and tumor suppressors (LKB1 and KLF6), which have causal role in cancer initiation and progression." (PMID 28105922, 2016). "Recent reports examining CDH17+ cancer cells reveal that cell cycle progression is slowed after CDH17 knockdown." (PMID 25612318, 2015). "CDH17 was initially recognized as a peptide transporter and recent evidences uncover its other function in cancers." (PMID 24039755, 2013). "Therefore, CDH17 represents a class of TAA for cancer immunotherapy previously unappreciated, revealing novel insight into targeting selection." (PMID 40007813, 2025). "However, the role of “non-canonical”, tissue-specific cadherins, such as cadherin 17 (CDH17) in the context of cancer stem cell biology remains vastly unexplored." (PMID 40595509, 2025). "Importantly, CDH17 supports clonogenicity and cancer stemness by regulating LGR5, a Wnt-targeted gene and established intestinal stem cell marker." (PMID 41155133, 2025). "The MA demonstrated that CDH17 suppression significantly affected several hallmarks of cancer." (PMID 41155133, 2025). "Notably, CDH17 knockdown not only significantly inactivated this pathway but also diminished cancer stemness and enhanced the proliferation and chemosensitivity of these clusters." (PMID 39994505, 2025). "Therefore, based on our SR/MA, we propose a schematic mechanism of Wnt/β-catenin pathway in cancer biology mediated by CDH17." (PMID 41155133, 2025). "A sex-stratified subgroup analysis revealed a significant negative association between CDH17 expression and cancer progression in males (OR = 0.60, 95% CI: 0.37 to 0.96, p = 0.04) but not in females (p = 0.43)." (PMID 41155133, 2025). "Furthermore, we compared the thermal killing effect between CR‐modified bacteria displaying Nb289 nanobody (Nb289‐MG1655‐CR) and the C9 control nanobody (C9‐MG1655‐CR) in CDH17‐overexpressing MKN45 cancer cells." (PMID 38888519, 2024).
cancer (continued). "Moreover, the targeted biohybrid bacteria Nb289‐MG1655‐CR can exert a more pronounced thermal killing effect on CDH17‐overexpressing cancer cells due to the selectivity of Nb289 to CDH17 molecules." (PMID 38888519, 2024). "Together, these results demonstrate that E8 nanobody could efficiently deliver anti-cancer payloads into CDH17-expressing GC." (PMID 36435809, 2022). "Thus, CDH17 has been regarded as a cancer biomarker for prognosis and an oncogene for cancer intervention." (PMID 36435809, 2022). "The results indicate that E8-PE38 could be applied on CDH17-positive GC cancers with 5-FU together, implying the great promise of E8-PE38 immunotoxin for GC therapy." (PMID 36435809, 2022). "Cadherin 17 can also influence the progression of certain cancers." (PMID 36152751, 2022). "In grade 3 cancer, the CDH17-positive ratio was higher than the HER2-positive one." (PMID 31605356, 2020). "Moreover, immunohistochemical analysis of sections of lungs and spines collected 28 days after subcutaneous injection of FP10SC2 cells into mice revealed the clear presence of cadherin-17-positive metastatic cancer cells in both the lungs and spines." (PMID 28197418, 2017). "It indicated that the CDH17 expression may contribute to cancer cell proliferation and colony formation ability in AGS cells." (PMID 24465527, 2014). "This discrepancy could be explained by the utilization of different cancer cell type and indicates significant differences in the molecular mechanism of action of CDH17 between GC and HCC." (PMID 24465527, 2014). "Whether Lic5 would affect the cell adhesive function of cancer cells remains to be further characterized, but our findings clearly suggested targeting the extracellular domain of CDH17 by Lic5 can inactivate the Wnt/β-catenin pathway." (PMID 24039755, 2013). "The involvement of CDH17 in tumorigenesis is versatile depending on cellular context, such that either up-regulation or down-regulation of this molecule is found in different cancers, including pancreatic cancers, gastric cancers and colorectal cancers." (PMID 24039755, 2013). "Indeed, this deregulated expression of CDH17 in cancers suggests this molecule as clinical indicator for disease status and severity." (PMID 24039755, 2013). "CDH17 is almost exclusively expressed in the intestinal cells of both embryonic and adult small intestine and colon, and is considered a selective marker of colon cancer cell lines, being expressed in 35 of the 54 epithelial-like colon cell lines described in the cancer cell line encyclopedia." (PMID 40595509, 2025). "This review assesses whether CDH17 is a viable therapeutic target across various cancer models." (PMID 41155133, 2025). "Underlying mechanism is unique location of CDH17 at tight junction between normal intestinal epithelial cells and thereby ‘masked’ in healthy tissues, while cancer cells’ lack of polarity exposes CDH17 expression enhancing susceptibility to CAR-T-mediated killing." (PMID 40007813, 2025). "Therefore, the data might contain valuable information on the clinical significance of CDH17 in human cancer." (PMID 31516924, 2019). "Our findings demonstrate that both CDH17 and SLC38A5 silencing are required for enhanced cancer cell sensitivity to 5-FU, irinotecan, oxidative stress, and anoikis." (PMID 40595509, 2025). "Furthermore, the synergistic potential of multiple proteins (e.g., CDH17 and CEACAM5) may amplify risk through either additive or interactive mechanisms, which is consistent with the rationale for multi-target combination therapies in cancer." (PMID 41049426, 2025). "In the spectrum of 33 human cancer types, GUCY2C demonstrates a similar expression pattern to CDH17." (PMID 40721409, 2025). "Next, we examined the binding and internalization activities of these six CDH17 x GUCY2C bsAbs in SW1463 and LS1034 cancer cells." (PMID 40721409, 2025).
cancer (continued). "The biohybrid bacteria Nb289‐MG1655‐CR exhibited a stronger killing effect on CDH17‐overexpressing MKN45 cancer cells than C9‐MG1655‐CR, indicating that CDH17 molecules on cancer cells captured more biohybrid bacteria Nb289‐MG1655‐CR." (PMID 38888519, 2024). "The protein biomarkers identified, such as CK7, CDH17, MLPH, FABP1, and NARR, can be used for differential diagnosis between the two cancers in primary healthcare institutions using IHC staining." (PMID 38608841, 2024). "CDH17 and SATB2 were excellent potential biomarkers for diagnosing metastatic colorectal adenocarcinoma and pulmonary enteric malignancy." (PMID 37719843, 2023). "CDX2 have emerged as important modulators of cancer aggressiveness and can influence the viability of HCC cells by transcription regulating oncogene CDH17." (PMID 34147074, 2021). "Therefore, CDH17-targeted imaging could more detect cancer compared with HER2-targeted imaging." (PMID 31605356, 2020). "In this review, we will discuss the structural and functional properties of cadherin 5 (CDH5), cadherin 6 (CDH6) and cadherin 17 (CDH17), as well as their pathological implications in cancer progression and metastasis." (PMID 31324051, 2019). "High expression of CDH17 in cancer cells correlates in general with a high expression of the intestine-specific transcription factor CDX2, which regulates CDH17 expression and plays a key role in the intestinal epithelial development and differentiation." (PMID 31324051, 2019). "Immunostaining patterns of CDH17 and CLDN18 were investigated in whole sections of cancer tissue from representative cases (9 cases for CDH17 and 5 cases for CLDN18), including primary tumors and nodal metastases to remove some of the focal biases of TMAs." (PMID 27580354, 2016). "We believe that these data suggest that [89Zr]Zr-DFO-D2101 could be a valuable agent for the clinical immunoPET of CDH17-positive PDAC and other cancers that express the antigen." (PMID 38625402, 2024). "In contrast, the control nanobody C9 was undetectable in these cells, and the CDH17‐negative cancer cell line MC38 showed no signal for all three nanobodies." (PMID 38888519, 2024). "Finally, RT-PCR and WB showed that CDH17, IGF2BP1, IGFBP1, ABCC2, and HMGA2 were differently expressed between human lung fibroblast (HLF) cells and cancer cells." (PMID 35903696, 2022). "For total protein levels, CDH6 was highly expressed in ovarian (OVCAR3 and SKOV‐3) and renal (RCC4 and 786‐O) cancer cell lines except in CAKI‐1 and A‐2780, while CDH17 was expressed in all cell lines, with RCC4, 786‐O, and OVCAR3 exhibiting the highest amounts." (PMID 33715292, 2021). "The sample size in the present study is limited and there is no report of large-scale CDH17 expression analysis in cancer specimens." (PMID 31605356, 2020). "The percentage of CDH17-negative primary cancer and CDH17-positive LN metastasis specimens was 28.6% (4/14), and the percentage of CDH17-negative primary cancer and CDH17-negative LN metastasis specimens was 71.4% (10/14)." (PMID 31605356, 2020). "An array of mutations in splicing cis-acting sequences include those of LKB1 (liver kinase B1), KIT (v-kit Hardy-Zuckerman 4 feline sarcoma viral oncogene homolog), CDH17 (cadherin 17), KLF6 (Kruppel-like factor 6) and BRCA1 (breast cancer gene 1) in many types of cancers." (PMID 32905346, 2020). "Cadherin-17 (CDH17, LI-cadherin) is a non-classical cadherin with restricted expression in normal gastrointestinal epithelium, emerging as a multifunctional molecule in cancer." (PMID 41928253, 2026). "The second mutated gene in S1 was CDH17, which has been shown to promote tumorigenesis and metastasis through Wnt-signaling and the third, the LMLN gene, which encodes a zinc-metallopeptidase, has not previously been implicated in cancer." (PMID 26497854, 2015).
cancer (continued). "Since CDH17 in cancer cell membrane could mediate the internalization of the corresponding nanobodies and nanobody‐modified extracellular vesicles, we also demonstrated here that Nb289‐engineered bacteria MG1655 could be efficiently internalized by CDH17‐positive cancer cells in vitro and in vivo." (PMID 38888519, 2024). "Still, the role of non-classical (i.e. cadherin 17 (CDH17)) and desmosomal cadherins in EMT and other cancer processes remains poorly understood." (PMID 38263178, 2024). "Taken together, our results demonstrates that E8 nanobody has the superb targeting ability towards CDH17-positive tumors and could efficiently deliver toxin PE38 to control cancer growth without detectable adverse events." (PMID 36435809, 2022).
adenocarcinoma (8 papers, 2004 to 2025). A common cancer characterized by the presence of malignant glandular cells. "CDH17 expression was retained in thirteen of 14 (93%) CD-associated adenocarcinomas and ≥ 40% extent expression was seen in 12 cases (86%), 9 of them showed ≥ 75% extent expression." (PMID 39164422, 2025). "High levels of CDH17 have also been linked to metastatic spread and poor prognoses in patients with several adenocarcinomas." (PMID 38625402, 2024). "Remarkably, abnormal CDH17 expression has been described as a diagnostic marker of adenocarcinomas of the digestive system, with higher sensitivity than CDX2." (PMID 30024920, 2018). "Seven of 13 (54%) CDH17-positive CD-associated adenocarcinomas were positive for CLDN18." (PMID 39164422, 2025). "CDH17 was considered as a tissue-specific diagnostic marker for adenocarcinomas." (PMID 39478862, 2024). "Several studies described CDH17 expression in adenocarcinoma of the digestive system, and it is considered a useful biomarker of adenocarcinomas with intestinal phenotype." (PMID 39164422, 2025). "CDH17 has been reported to be present in a wide variety of adenocarcinomas, including those of the digestive system." (PMID 40725206, 2025). "Herein, we report the synthesis, characterization, and in vivo validation of a 89Zr-immunoPET probe for the delineation of CDH17 expression in adenocarcinoma." (PMID 38625402, 2024). "In contrast, in CRC, Cadherin-17 (CDH17) is overexpressed and has been suggested as a useful biomarker for identifying adenocarcinomas in a metastatic stage." (PMID 32295170, 2020). "However, several types of adenocarcinoma cells overexpress CDH17, fueled by phosphorylation cascades within the ⍺2β1 integrin, Wnt/β-catenin, and Ras/Raf/MEK/ERK pathways." (PMID 38625402, 2024). "Indeed, even the most cursory perusal of the literature reveals that several adenocarcinomas abundantly express CDH17." (PMID 38625402, 2024). "Our results showed that regardless of adenocarcinoma or dysplasia, CDH17 expression was retained in most CD-SBNs and CLDN18 expression was seen in 56% of CD-SBNs with a strong association with the expression of gastric mucins." (PMID 39164422, 2025).
GI tumors (5 papers, 2017 to 2025). "In this study, we engineered nanobody-based chimeric antigen receptor (CAR) natural killer (NK) cells targeting cadherin 17 (CDH17) for the treatment of GI tumors." (PMID 40487639, 2025). "Hence, CDH17 is highly sensitive for gastrointestinal tumors." (PMID 28969003, 2017). "In the literature, the sensitivity for CDH17 has been reported to be 96–100% for colorectal, 18–57% for pancreatic, 25–90% for gastric, and 39–82% for esophageal AC, and often higher than CDX2 for the upper GI tumors." (PMID 37349623, 2024).
infection (3 papers, 2012 to 2022). The state of being infected such as from the introduction of a foreign agent such as serum, vaccine, antigenic substance or organism. "Therefore, the results of this assay suggest that CD133, CDH17, and VAPA partially contribute to infection in ACE2-expressing cells." (PMID 36152751, 2022). "In the infection assays using cells expressing each candidate molecule alone, almost no infection was observed, which indicated that CD133, CDH17, and VAPA were not the primary receptors for the SARS-CoV-2 spike protein." (PMID 36152751, 2022).
cancers of digestive system (2 papers, 2022 to 2024). "Cadherin 17 (CDH17) is a membrane protein highly expressed in cancers of digestive system." (PMID 36435809, 2022).
CDH17 also shares sentences with these, for which no sentence is quoted: cholangiocarcinoma (4 papers); esophageal cancer (2); prostate carcinoma (2); bladder adenocarcinoma (1); bladder cancer (1); carcinoma of the uterine cervix (1); cervical adenocarcinoma (1); cervical cancer (1); cleft lip/palate-ectodermal dysplasia syndrome (1); colorectal (1); colorectal polyps (1); Crohn disease (1); cryptococcosis (1); cyst (1); diabetes (1); endometrioid carcinoma (1); eosinophilia (1); gynecological cancers (1); Hepatic steatosis (1); hyperlipidemia (1); Intestinal Diseases (1); intraepithelial neoplasia (1); Kidney Diseases (1); lymphoepithelioma (1); metabolic disorders (1); metanephric adenoma (1); metastasis (1); mucinous ovarian cancer (1); neuroendocrine carcinoma (1); parasite infections (1).
A further 8 diseases each share a sentence with CDH17 in 1 paper.